RB1 (RB transcriptional corepressor 1)
Diseases named in the same sentence as RB1 in open-access papers (continued):
Sharing a sentence is not in itself a finding about the gene and the disease.
tumor (continued). "We and others have previously shown that, when tumour DNA is unavailable, cell-free DNA (cfDNA) derived from aqueous humour (AH) can be used to identify somatic RB1 pathogenic variation." (PMID 38672657, 2024). "RB is thought to be related to the mutation or inactivation of two copies of the retinoblastoma gene (RB1), the tumor suppressor gene, and caused by a mutation of RB1 programming retinoblastoma protein (pRB)." (PMID 38920989, 2024). "When comparing primary tumor sites, HG colorectal NENs had a higher frequency of tumors with Rb1 loss (50.0%), followed by HG gastroesophageal NENs (30.0%) (p = 0.03)." (PMID 38729995, 2024). "The germline variant in RB1 alone was likely sufficient for the cell cycle deregulation that triggered tumorigenesis in all three neoplasms." (PMID 39596402, 2024). "We confirmed tumor and non-tumor origins of the cells by RB1 mutation, MYCN FISH analyses and examined the expression of cancer and stroma-related marker proteins." (PMID 39695086, 2024). "DLL-3 demonstrated differential expression in NE PCa tumours compared to adenocarcinoma, correlated with NE markers, RB1 loss and aggressive clinical features." (PMID 39682746, 2024). "Type 1 tumours harbour few genetic alterations other than the initiating RB1-inactivating mutations and corresponds to differentiated tumours expressing mature cone markers." (PMID 37606819, 2024). "Tumorsphere cultures showed the original tumor’s RB1 mutation, while stroma-like cells were RB1 wildtype." (PMID 39695086, 2024). "We also observed reduced gut microbiota diversity in the two distinct mouse models that grew the largest tumours, in particular those with loss of both Pten and Rb1, an alteration frequently observed in metastatic PCa patients." (PMID 38654015, 2024). "We and others have previously shown that the analysis of cell-free DNA from aqueous humour can be used as a surrogate for tumour DNA for the detection of somatic RB1 mutations, although patient numbers, in all publications, have been relatively small." (PMID 38672657, 2024). "As a tumour suppressor gene, RB1 is functionally compromised in many tumours owing to mutation, deletion or phosphorylation inactivation." (PMID 38862740, 2024). "For example, in patient P12 all 27 undetected putative metastatic driver mutations—including an inactivating 5-bp deletion frameshift mutation in RB1 at N258—would have to have been sequentially acquired in, at most, 1% of primary tumor cells." (PMID 38321573, 2024). "The tumor is primarily caused by mutations in the retinoblastoma gene (RB1) located on chromosome 13q14." (PMID 38610910, 2024).
tumor (continued). "Taken together, these preclinical data indicate that RB1-deficient tumor growth and metastasis are vulnerable to ferroptosis induction." (PMID 36928314, 2023). "The RB1 c.13delA mutation was found in 33% (5/15) of primary tumor regions and 36% (4/11) of metastatic regions." (PMID 38098507, 2023). "Approximately 40% of germline CPGs have been found with somatic variants in tumours as drivers and some of these genes have been shown to play a role in tumourigenesis, with RB1 being the classical example." (PMID 36833203, 2023). "Previous studies demonstrated that loss of RB1 is associated with decreased leukocyte recruitment, resulting in tumor immune evasion across a variety of cancer histologies." (PMID 37046760, 2023). "This protein is encoded by the RB transcription corepressor gene 1 (Rb1), which was the first tumor suppressor gene discovered." (PMID 38002335, 2023). "As already mentioned, all cells of hereditary RB patients carry a germline mutation in one allele of RB1, a tumor suppressor gene." (PMID 38001596, 2023). "The right panels show bar graphs for each respective ctDNA RB1 alteration: the x-axis represents timepoints (BL = baseline, mos = months from baseline), and the y-axis shows plasma circulating tumor RB1 variant allele frequency percentage." (PMID 36735656, 2023). "The x-axis represents time in minutes and the y-axis shows plasma circulating tumor RB1 variant allele frequency percentage." (PMID 36735656, 2023). "Since RB1 loss-of-function mutations occur across various tumor types, we also examined the effect of PRMT5 silencing in other RB-deficient cancer cell lines." (PMID 37502925, 2023). "Seven heterozygous protein-truncating mutations were found in tumor suppressor genes including RB1, FBXO11, FAT1, KMT2D, KMD6A, ACVR2A and ZFHX3." (PMID 36702998, 2023). "SNV profiling showed strong concordance in the detection of pathogenic RB1 variants between the AH and tumor samples." (PMID 37239954, 2023). "This tumor mainly occurs due to biallelic mutation of the RB1 gene on chromosome 13; but other events, such as chromosomal anomalies (isochromosome 6p or extra copies of chromosome 1p) or epigenetic changes, are involved in RB development." (PMID 38069286, 2023).
tumor (continued). "The emergence of some driver gene mutations during treatments was detected by circulating tumor DNA analysis, revealing mutations in RB1 and to a larger extent in PIK3CA and the ERα gene ESR1 itself." (PMID 36869202, 2023). "The retinoblastoma susceptibility gene (Rb1), as a tumor repressor gene, has critical effects on multiple cellular processes, such as ferroptosis, apoptosis, and DNA repair." (PMID 36851083, 2023). "In line with this possibility, poorly differentiated cells in MYCN-amplified RB have been shown to be more responsive to chemotherapy than differentiated tumor cells in RB1-deficient RB with featured rosettes." (PMID 36726110, 2023). "The tumor is caused by the inactivation of the gene RB1, a tumor suppressor gene located on chromosome 13q14, and it arises from immature retinal cells." (PMID 36362243, 2022). "Loss of Rb1 accelerated the early stages of tumor development as indicated by an increased number of adenomas and tumor burden in younger mice, and it increased tumor grade." (PMID 35368709, 2022). "Two patients died due to a third malignant neoplasm; one of them received radiation on a tumor bed during the first treatment, and the other had a germline RB1 mutation." (PMID 35200584, 2022). "One MYCN-amplified tumor displayed complete RB1 loss (RB1–/–), caused by a germline frameshift on exon 5 followed by loss of heterozygosity." (PMID 36245757, 2022). "Tumor samples were selected based on young age at diagnosis, mutation in RB1 in a 5′-exon and presence of LOH in the tumor." (PMID 35565295, 2022). "Only one mutation in a SETD7 lysine methylation site was found, consisting of a K873E missense mutation in the tumour suppressor RB1, in only one sample." (PMID 36551516, 2022). "The tumor sample with the MYCN-amplified RB1-deficient (MYCNARB1–/–) background clustered within another subbranch in branch 1 and separated from MYCNARB1PRO tumors." (PMID 36245757, 2022). "Cell cycle-related genes, including CCND1, CDK4, CDKN2A, and RB1, were frequently mutated in MSCs, PCs, and tumor cells." (PMID 35087207, 2022). "Inactivation of both copies of the RB1 gene is essential for oncogenesis, and one normal allele of the RB1 gene is protective against tumor development." (PMID 36714839, 2022). "The associations of RB1 with immune infiltration and immune checkpoints were studied by the Tumor Immune Estimation Resource (TIMER 2.0) and the Gene Expression Profiling Interactive Analysis (GEPIA)." (PMID 35299734, 2022). "The drug sensitivity analysis of key mutation showed when RB1 mutation occurs, the efficacy of six anti‐tumour drugs has changed significantly (p < 0.05)." (PMID 35735060, 2022). "This hypotesis was based on the evidence from one patient with matched pre/post-CDK4/6i tumor sample and the relatively low frequency of acquired RB1 point mutations after treatment with palbociclib." (PMID 36071033, 2022). "While differentiating stem cells with a mutation in RB1 into retina, we observed reduced differentiation potential but enhanced proliferation—general hallmarks of tumor development." (PMID 35565295, 2022).
tumor (continued). "Epidemiological and molecular studies of the tumour led to the discovery of the first tumour suppressor gene, the Rb susceptibility gene RB1." (PMID 35620002, 2022). "The tumor develops when both alleles of the RB1 gene suffer a loss of function, making cell cycle control unfeasible." (PMID 36507141, 2022). "For tumor formation, inactivation of the second allele of RB1 needed to occur in the xenografts, which was observed with low frequency only." (PMID 35565295, 2022). "According to a data analysis based on 12 tumor types, RB1 somatic mutations or deletions are detected in a large fraction of colorectal, breast, uterine, ovarian, bladder, and lung cancer." (PMID 35361964, 2022). "We also found that the two subtypes exhibited significant differences in tumor size, RB1 mutation, and laterality." (PMID 35664300, 2022). "The molecular cancer mechanism is related to a mutation of the RB1 gene, a tumor suppressor gene located in region 1, band 4, of the long arm of chromosome 13 (13q14)." (PMID 36507141, 2022). "The retinoblastoma susceptibility gene (RB1) is the first tumor suppressor gene discovered and a prototype for understanding regulatory networks that function in opposition to oncogenic stimuli." (PMID 35368709, 2022). "RB1 was the first tumour suppressor gene found, and the protein encoded by RB1 is a negative regulator of the cell cycle." (PMID 36267410, 2022). "Loss of Rb1 has been found to cause cell proliferation and tumor formation in humans, while expression of Rb1 eliminates cell proliferation caused by loss of Rb1 in humans cells and mouse models." (PMID 35399296, 2022). "RB1 is a chromatin‐associated tumour suppressor that can limit the transcription of cell cycle genes." (PMID 35969010, 2022). "In 95% of the cases, tumor arises due to the biallelic loss of the tumor suppressor gene RB1, and its development is sustained by genetic and epigenetic factors that lead to leukocoria, a white pupillary reflex." (PMID 36338723, 2022). "The RB1 gene was mutated during bone metastasis, and tumor heterogeneity was less in the elevated platelet group." (PMID 34799997, 2022). "The RB1 gene was mutated during bone metastasis, and tumor heterogeneity was less in the elevated PLT group." (PMID 34799997, 2022). "We found mutation of RB1, a well-known tumor suppressor, was also enriched in tumors of stemness subtype I with a relatively low mutation rate." (PMID 35158838, 2022).
tumor (continued). "It should be emphasized that this an alternative epigenetic model of pRB restoration is shown in non-RB1-mutational tumor cells in our study." (PMID 36175480, 2022). "The first identified tumor suppressor was the retinoblastoma gene, RB1, which causes pediatric malignancy of the eye after biallelic inactivation." (PMID 34983823, 2022). "Approximately 90% of children with RB are diagnosed between birth and five years old, and the tumor has been associated with the RB1 mutation." (PMID 35982972, 2022). "Analysis of the relationship between mutation status and tumor focality indicated that multifocality in RB was dependent on germline RB1 mutation, confirming a higher tendency to have a germline RB1 mutation in patients with multifocal RB." (PMID 36173648, 2022). "Four patients (16.7%) progressed during therapy, and they all died; one of them received radiation on a tumor bed during the first treatment, and two of them had a germline RB1 mutation." (PMID 35200584, 2022). "Mutations in RB1 have been reported in the circulating tumor DNA (ctDNA) of several BC patients and in patient-derived tumor xenograft models." (PMID 34244855, 2021). "Knudson6 proposed that two separate mutational events (M1 and M2), which result in loss or inactivation of both copies of the RB1 gene, are required to initiate the tumor." (PMID 34003213, 2021). "One of the best-known genes implicated in tumor development and the first ever described tumor suppressor gene is Retinoblastoma 1 (RB1), located at chromosome 13q14.2." (PMID 33802620, 2021). "Mouse models of retinoblastoma and neuroblastoma show that Rb1 loss in MYCN-driven tumors accelerates tumor progression and shortens survival time." (PMID 34099734, 2021). "Subsequently, a separate report indicated that six of eight tumours with MYCN amplifications also contained at least one RB1 mutation." (PMID 33670346, 2021). "We also published a comprehensive workflow for the AH liquid biopsy that included simultaneous whole-genome SCNA analysis, RB1 pathogenic variant detection, and tumor fraction estimation from a single 100μL sample of AH from RB eyes." (PMID 33805776, 2021). "Tumoral genomic information was detected in 100% of diagnostic aqueous humor samples, including single nucleotide variants in the RB1 tumor suppressor gene and large-scale somatic chromosomal alterations." (PMID 33805776, 2021). "Assessment of all four RB1-detected mutations in the two Rb tumor samples by Mutation Taster program indicated that the mutant RB1 transcripts were most likely to undergo nonsense-mediated decay, resulting in loss of RB1 protein." (PMID 34003213, 2021).